HAMP (hepcidin antimicrobial peptide)
Description:
Liver-produced hormone that constitutes the main circulating regulator of iron absorption and distribution across tissues. Acts by promoting endocytosis and degradation of ferroportin/SLC40A1, leading to the retention of iron in iron-exporting cells and decreased flow of iron into plasma. Controls the major flows of iron into plasma: absorption of dietary iron in the intestine, recycling of iron by macrophages, which phagocytose old erythrocytes and other cells, and mobilization of stored iron from hepatocytes. Has strong antimicrobial activity against E.coli ML35P N.cinerea and weaker against S.epidermidis, S.aureus and group b streptococcus bacteria. Active against the fungus C.albicans. No activity against P.aeruginosa.
Synonyms: LEAP-1; PLTR; HEPC; LEAP1; HFE2B
Tractability: Small molecule: a structure with a bound ligand is known. Antibody: a drug acting on it is in phase 1 trials; UniProt places it where antibodies can reach, with high confidence; UniProt predicts a signal peptide or a membrane-spanning region; its Gene Ontology location is reachable by antibodies, with medium confidence.
Target class: Secreted protein
Gene: Protein-coding gene on chromosome 19 (35,280,716 to 35,285,143, forward strand). Ensembl gene ENSG00000105697.
Subcellular location: Secreted
Gene Ontology:
Molecular function: hormone activity; transporter regulator activity
Biological process: intracellular iron ion homeostasis; multicellular organismal-level iron ion homeostasis; negative regulation of intestinal absorption; negative regulation of iron export across plasma membrane; positive regulation of proteasomal ubiquitin-dependent protein catabolic process; response to iron ion; defense response to bacterium; immune response; negative regulation of iron ion transmembrane transport; negative regulation of transcription by RNA polymerase II; inorganic ion homeostasis; monoatomic cation homeostasis; signal transduction
Cellular component: extracellular region
Genetic constraint (gnomAD): Loss-of-function variants: 6 observed, 7.99 expected, observed/expected ratio (o/e) 0.75, 90% interval 0.41 to 1.46. That is too few expected variants to judge how well the gene tolerates losing a copy. Missense variants: 96 observed, 104.62 expected, observed/expected ratio (o/e) 0.92, 90% interval 0.78 to 1.09. Synonymous variants: 50 observed, 39.75 expected, observed/expected ratio (o/e) 1.26, 90% interval 1 to 1.59.
Gene-disease validity (ClinGen):
ClinGen rates the evidence that HAMP causes each of these diseases.
hemochromatosis type 2B (autosomal recessive): Definitive. Any hemochromatosis type 2 in which the cause of the disease is a mutation in the HAMP gene.
Homologues: Orthologues: chimpanzee HAMP (99% identical), macaque HAMP (95% identical), pig HAMP (70% identical), dog HAMP (69% identical), rabbit HAMP (68% identical), guinea pig HAMP (65% identical), mouse Hamp (58% identical), rat Hamp (57% identical), mouse Hamp2 (52% identical), zebrafish hamp (30% identical).
Diseases named in the same sentence as HAMP in open-access papers:
HAMP is named in the same sentence as 109 diseases in open-access papers, as found by Europe PMC text mining. Sharing a sentence is not in itself a finding about the gene and the disease. The quoted sentences say what the papers report.
hemochromatosis (31 papers, 2012 to 2026). A disorder of iron metabolism characterized by a triad of HEMOSIDEROSIS; LIVER CIRRHOSIS; and DIABETES MELLITUS. "In this case report, we describe hereditary hemochromatosis related to HAMP gene mutation in Fuyang City, China, for the clinician’s reference." (PMID 39005658, 2024). "In this case report, we described hereditary hemochromatosis related to a mutation in the HAMP gene in Fuyang City, China, as a reference for clinicians." (PMID 39005658, 2024). "In summary, the incidence of hereditary hemochromatosis related to mutations in the HAMP gene is rare in China." (PMID 39005658, 2024). "In this case the simulation of hemochromatosis is achieved by silencing hepcidin synthesis at the transcription level (HAMP-/-) instead of the HFE-/- mutation." (PMID 30608934, 2019). "The low expression level of Hepcidin is usually seen whether there is mutation in HAMP gene or a gene named Hemochromatosis (HFE), that codes for HFE protein in case of HFE disease (Le Gac & Férec, 2005)." (PMID 32588561, 2020). "Adipocytes express common regulators of iron homeostasis including iron-regulatory proteins (e.g. ferritin and hepcidin), as well as iron-related proteins with restricted tissue expression (e.g. TfR2-Transferrin Receptor 2, HFE-encoding Human hemochromatosis protein, and HAMP-hepcidin)." (PMID 28651003, 2017). "Hereditary hemochromatosis is caused by mutations in iron regulatory genes, including HAMP (hepcidin gene), HFE (hemochromatosis gene), TFRC (transferrin receptor), HJV (hemojuvelin), and SLC40A1 (ferroportin), and heterozygous mutations in BMP6 pro-peptide." (PMID 40871742, 2025). "Mutations in five key genes - HFE (hemochromatosis), HJV (hemojuvelin), HAMP (hepcidin antimicrobial peptide), TfR2 (transferrin receptor 2), and FP (ferroportin) - are responsible for HH." (PMID 39114232, 2024). "It elucidates diverse inheritance patterns and clinical manifestations by exploring mutations in critical genes such as HFE (hemochromatosis), HJV (hemojuvelin), HAMP (hepcidin antimicrobial peptide), TfR2 (transferrin receptor 2), and FP (ferroportin)." (PMID 39114232, 2024). "SSD exerts the most powerful inhibitor of hepcidin antimicrobial peptide (HAMP), which is primarily involved in the maintenance of iron homeostasis and anemia of chronic disease and hemochromatosis." (PMID 36139460, 2022). "Hyperferritinemia with iron overload includes hemochromatosis (HH) due to mutation in HFE, HJV, HAMP, TFR2 and SLC40A1 gain-of-function mutations, hereditary iron loading anemias, and hypo-transferrinemia that are characterized by high TSAT." (PMID 34828384, 2021). "Non-HFE forms or atypical hemochromatosis involving HJV or hepcidin antimicrobial peptide (HAMP) mutations lead to juvenile or type 2 hemochromatosis, while the mutations in TfR2 cause an adult-onset form of type 3 hemochromatosis." (PMID 41010490, 2025). "Additionally, the expression of the HAMP gene in the kidney is increased in wild-type mice fed with a high-Fe diet but remains unaltered in hemochromatosis mice." (PMID 37445980, 2023). "These include a mutation in the hemochromatosis gene HFE causing the so-called HFE-associated hereditary hemochromatosis, which is most commonly found in individuals of European ancestry, and mutations in the hemojuvelin (HJV) or hepcidin gene (HAMP) causing juvenile HH." (PMID 36738308, 2023). "While the simulation differs slightly from the experiment, by causing hemochromatosis through mutation in the HAMP gene (hemochromatosis type 2B) rather than through the HFE gene (hemochromatosis type 1), the results are qualitatively similar to the experiments." (PMID 30608934, 2019). "A follow-up hereditary hemochromatosis genetic panel analyzed FTH1, FTL, HAMP, HFE, HJV, SLC40A1, and TFR2 genes." (PMID 39450139, 2024).
hemochromatosis (continued). "Notably, the distribution on polyribosimal fractions of hemochromatosis (HFE), hemojuvelin (HJV), and hepcidin (HAMP) transcripts, all genes that were previously reported to respond to miR-122, was found to be affected by the modulation of miR-122 levels." (PMID 37627157, 2023). "Neither novel HFE alleles nor deleterious alleles in TFR2, HAMP, and SCL40A1 were detected in referred hemochromatosis patients with p.H63D/p.H63D." (PMID 35895739, 2022). "As hemochromatosis can also be caused by other mutation in the HFE gene or so called non-HFE hemochromatosis genes (HJV, HAMP, TFR2), homozygosity for p.Cys282Tyr is neither sufficient nor necessary for the diagnosis hemochromatosis." (PMID 30514216, 2018). "In details, four genes of iron homeostasis (Hemochromatosis (HFE: C282Y, H63D), Ferroportin (FPN1: -8CG), Hepcidin (HAMP: -582AG), Transferrin (TF: P570S)), and the three major alleles of APOE (APOE2, APOE3, APOE4) were analyzed to explore causative interactions and synergies." (PMID 29518107, 2018).
iron overload (27 papers, 2010 to 2025). "Mutations of any gene in the HAMP regulatory machinery result in decreased HAMP transcription, which decreases hepcidin levels and causes iron overload." (PMID 39965404, 2025). "Mutations in HJV and HAMP causing juvenile iron overload have also been reported throughout the Asia Pacific region but remain extremely uncommon." (PMID 37067673, 2023). "Mutation in either HAMP gene or HFE gene causes Hepcidin protein deficiency that can lead to iron overload in beta thalassemia patients." (PMID 32588561, 2020). "This study aimed to analyze the association between three SNPs in promoter of HAMP, c.-582A > G, c.-443C > T, and c.-153C > T, with iron overload in β-thalassemia major patients." (PMID 32268883, 2020). "The genetic disease hereditary hemochromatosis (HH) is characterized by loss of function mutations in the HAMP pathway, leading to systemic iron overload." (PMID 30820238, 2019). "Iron overloading in haemochromatosis can be caused by mutation in the gene encoding hepcidin (HAMP) itself." (PMID 30995720, 2019). "In humans, three SNPs in the 5′ promoter region of HAMP are associated with severe iron overload including binding sites for SMAD and STAT3." (PMID 30301129, 2018). "Lately, two genetic variants in the HAMP promoter have been described as modulators of iron overload." (PMID 21143959, 2010). "The gene encoding hepcidin, HAMP, is mainly expressed in the liver in situations of iron overload." (PMID 21143959, 2010). "In addition, some studies support the concept that digenic inheritance of HFE and HJV or of HFE and HAMP mutations can lead to iron overload or may aggravate the phenotype." (PMID 22408404, 2012). "It has been demonstrated that HAMP gene knockout mice can develop intrahepatic iron overload at 2 months of age, and with increasing age, iron deposition both inside and outside of the liver increases rapidly." (PMID 39005658, 2024). "In terms of genetics, different types of hereditary hemochromatosis are caused by mutations in the HFE, hepcidin (HAMP), hemojuvelin (HJV), ferroportin (SLC40)A1, and transferrin receptor 2 (TfR2) genes that correspond to genetic disorders of iron overload." (PMID 32635533, 2020). "For this purpose, we compared serum hepcidin levels and hepatic hepcidin antimicrobial peptide (HAMP) gene expressions in NAFLD patients with various degrees of iron overload, to those of patients with other forms of acquired or genetic iron overload." (PMID 29871592, 2018). "Present research suggested that altered expressions of HAMP, HP and A2M genes might have contributed to induce iron overload in PCOS patients." (PMID 40057801, 2025). "Our study revealed that HAMP mRNA was decreased in PCSK7-knockdown HCC cells, further indicating that PCSK7 may be a candidate gene or modifier gene causing iron overload involved in HH." (PMID 35668470, 2022). "It is hypothesized that there could be relation between G71D of HAMP and H63D of HFE gene mutations with iron overload in case of Beta Thalassemia major in KP‐population." (PMID 32588561, 2020). "The severity of iron overload increases in the order from HFE-/- to TFR2-/- to HJV-/- or HAMP-/-." (PMID 30608934, 2019). "Other mutations, such as H63D in HFE or mutations in non-HFE genes like HAMP, HJV, TFR2, and SLC40A1 (FPN1), also contribute to iron overload but tend to have a variable clinical impact." (PMID 39323676, 2024). "In NAFLD with or without dysmetabolic iron overload, serum hepcidin and HAMP mRNA in liver correlate to body iron content but not to the degree of steatohepatitis or lipid status." (PMID 29871592, 2018). "The non-HFE HH gene, HAMP, is also known to be associated with Type 2B JH; TFR2, expressed almost entirely in the liver, also is involved with hepcidin synthesis and can lead to a form of iron overload that is similar to HFE HH, also without HFE involvement; this is known as Type 3 HH." (PMID 23817740, 2013).
iron overload (continued). "Levels of HAMP mRNA, serum and urinary hepcidin in controls (NAFLD patients without iron overload), DIOS and HFE-HH patients." (PMID 22586470, 2012). "Ratios of HAMP mRNA, serum and urinary hepcidin in controls (NAFLD patients without iron overload), DIOS and HFE-HH patients." (PMID 22586470, 2012).
hepatocellular carcinoma (24 papers, 2016 to 2024). A malignant tumor that arises from hepatocytes. "Studies have shown that dysregulated HAMP expression is associated with an increased risk of hepatocellular carcinoma." (PMID 33968297, 2021). "Our data showed HAMP expression significantly affected the cell cycle checkpoint and associated with the cell cycle of hepatocellular carcinoma." (PMID 31052210, 2019). "The HAMP gene, which encodes hepcidin, is transcriptionally repressed and closely associated with the hypermethylated signature on the gene promoter region in human hepatocellular carcinoma." (PMID 30591630, 2018). "As expected, BMP6 and BMP2 treatment, alone or in combination, induced HAMP mRNA in human Huh7 hepatoma cells." (PMID 36982241, 2023). "A recent study demonstrated that HAMP, as a tumor suppressor gene of hepatocellular carcinoma, downregulation contributes to proliferation, aggressiveness, and metastasis of hepatocellular carcinoma via the cyclin 4-dependent kinase-1/STAT3 pathway." (PMID 36585741, 2022). "In consistent, HAMP, the coding gene for hepcidin is mainly expressed in benign liver tissues but significantly reduced in hepatocellular carcinoma tissues." (PMID 34858857, 2021). "The effect of HCV NS5A protein on HAMP gene expression was evaluated with its ectopic expression in hepatoma cells by transient transfection, and the subsequent assessment of the relative HAMP gene promoter activity." (PMID 33247551, 2021). "We observed that transient transfection of hepatoma cell lines with HCV NS5A resulted in down‐regulation of HAMP promoter activity." (PMID 33247551, 2021). "Given that low expression of HAMP accelerated the proliferation and migration of hepatocellular carcinoma cell, we used the Gene Set Analysis of the TCGA to explore potential HAMP targets." (PMID 31052210, 2019). "To determine the effect of HAMP low expression on phenotypic properties in hepatocellular carcinoma cells, we used HAMP shRNA to knockdown HAMP expression and HAMP overexpression vector to induce HAMP overexpression." (PMID 31052210, 2019). "In HuH7, a human hepatoma cell line, leptin treatment resulted in increased HAMP mRNA, which was regulated by the JAK2/STAT3 signaling cascade." (PMID 30360386, 2018). "C2-ceramide treatment in human hepatocellular carcinoma (HepG2) cells was found to transcriptionally upregulate HAMP mRNA via the JAK/STAT3 signaling cascade." (PMID 30360386, 2018). "Here, we have shown a specific role for the lipid species, ceramide in the regulation of HAMP transcription via the activation of JAK/STAT3 signaling in human hepatoma cells." (PMID 26807955, 2016). "These ligands appropriately induced HAMP mRNA in human Huh7 hepatoma cells." (PMID 36982241, 2023). "Additionally, TCGA analysis demonstrated that hepatocellular carcinoma in patients with lower HAMP expression had a higher disease recurrence rate and metastasis grade." (PMID 31052210, 2019). "Interestingly, a recent report has shown that HAMP expression is supressed in hepatocellular carcinoma through hypermethylation of CpGs within the gene promoter." (PMID 29771984, 2018). "The knockdown of HAMP induced FTH expression in human hepatoma cell lines." (PMID 29899851, 2018). "We assumed that downregulation of HAMP could increase the hepatocellular carcinoma invasiveness." (PMID 31052210, 2019). "To confirm these findings, we treated hepatoma cells with surfen, which reduced IL6-induced stimulation of HAMP expression." (PMID 31315930, 2019). "Collectively, GSEA analysis of TCGA indicated that low HAMP expression affects the activation of the G2M checkpoint to influence the cell cycle of the hepatocellular carcinoma, which contributes the aggressive HCC." (PMID 31052210, 2019).
hepatocellular carcinoma (continued). "In the human hepatoma Huh7 cell line, upregulation of hepcidin expression through the canonical BMP pathway increased H3K9ac at the HAMP promoter, while suppression of HAMP mRNA expression using a BMP receptor inhibitor (LDN193189) reduced enrichment for this mark." (PMID 28864822, 2017). "Likewise, we found that activin B and, to a lesser extent, activin A, induced HAMP mRNA in HepG2 hepatoma cells at 4 h posttreatment but did not significantly induce ID1 mRNA." (PMID 28893916, 2017).
anemia (21 papers, 2011 to 2025). A reduction in the number of red blood cells, the amount of hemoglobin, and/or the volume of packed red blood cells. "On the other hand, increased risk of invasive Salmonella infection has been observed in HAMP (hepcidin gene) knockout studies, suggesting that the low hepcidin levels reported in children with severe anaemia may contribute to NTS susceptibility." (PMID 32972031, 2020). "We found that Sox2 as a novel factor to bind with HAMP promoter to negatively regulate HAMP expression, which may be further implicated as a therapeutic option for the amelioration of HAMP-overexpression-related diseases, including iron deficiency anemia." (PMID 25943891, 2015). "In contrast to the SCD mice, in the mouse model of phenyl hydrazine-induced anemia, HAMP expression was decreased in renal distal tubules." (PMID 37445980, 2023). "These pro-inflammatory cytokines further induce the expression of hepcidin antimicrobial peptide, a critical mediator of anemia of inflammation, which decreases serum iron availability and correlates with serum ferritin." (PMID 29535765, 2018). "In conclusion, our study presents important evidence for the regulation of HAMP expression by Sox2, and this finding can supply a potential therapeutic option to treat anemia of chronic disease." (PMID 25943891, 2015). "It was also proposed that the repression of HAMP in conditions of hypoxia, anaemia and erythropoeisis is through a common transcription factor atonal homologue 8 (ATOH8)." (PMID 26182354, 2015). "This link between HAMP and ferroportin in cells such as enterocytes, hepatocytes and monocytes plays a key role in the so-called anemia of infection or chronic disease." (PMID 24795646, 2014). "Given the importance of hepcidin in the pathophysiology of inflammation-induced anemia, the scientific community has given considerable attention to regulators of HAMP gene expression, besides the well-known IL-6 stimulator via the JAK2/STAT3 signaling pathway." (PMID 40126293, 2025). "Thus, HAMP inhibitors, which are used to treat anemia, might recreate in humans the state seen in bats under filoviral infection." (PMID 36851566, 2023). "In addition, Hamp expression did not change significantly during infection, suggesting that HAMP may not contribute to the anemia and downregulation of FPN during ST infection in AcB61 mice." (PMID 28507548, 2017).